BDNF (brain derived neurotrophic factor)
Diseases named in the same sentence as BDNF in open-access papers (continued):
Sharing a sentence is not in itself a finding about the gene and the disease.
Aphasia (continued). "We conducted a literature search through PubMed and Google Scholar with the following terms: “brain derived-neurotrophic factor” and “aphasia” for original articles from January 2000 until June 2020." (PMID 34367374, 2021). "In this investigation we examined two questions related to aphasia recovery and BDNF genotype." (PMID 40658687, 2025). "It is also possible that effects of differences in BDNF secretion might accumulate gradually, showing only when long-term aphasia recovery in the chronic phase is observed." (PMID 40658687, 2025). "However, future research would be required to understand better the relationship between BDNF genetic variations and poststroke aphasia." (PMID 34367374, 2021). "In addition, participants in the atypical BDNF group had an overall greater aphasia severity on the revised-WAB-AQ than that of typical BDNF carriers of chronic stroke." (PMID 34367374, 2021). "Therefore, we hypothesized that similar manifestations would be seen in PSA and that piTBS might alter the level of BDNF, which plays an important role in aphasia recovery." (PMID 38725649, 2024). "This suggests that patients with non-fluent aphasia have a significant increase in serum BDNF levels in peripheral blood after low-frequency rTMS treatment." (PMID 35711903, 2022). "Two recent studies focused on chronic non-fluent aphasia and tDCS outcome related markers (resting state fMRI and BDNF levels) in seven and nine patients, respectively." (PMID 31105510, 2019).
astrocytoma (12 papers, 2010 to 2025). "NGF expression was reported to be increased, whereas BDNF expression was reduced, both in tumor samples and cerebrospinal fluid (CSF), in children with low-grade astrocytomas and ependymomas." (PMID 32906676, 2020). "Among these compounds, erinacine C appeared particularly interesting as this substance was able to induce both Nerve Growth Factor β (NGF) and Brain-Derived Neurotrophic Factor (BDNF) expression in the astrocytoma cell line 1321N1." (PMID 33066380, 2020). "In our study, the undifferentiated C62B rat astrocytoma cells were capable of synthesizing BDNF after treatment with duloxetine or DOV 216,303." (PMID 22581450, 2012). "Expression of NGF and BDNF has been found in samples of human astrocytoma." (PMID 32906676, 2020). "Interestingly, a comparative investigation of the neuroprotective properties of hericenone C and deacylhericenone showed that the BDNF mRNA expression in human astrocytoma cells (1321N1) and the protection against H2O2-induced oxidative stress was considerably higher in the case of deacylhericenone." (PMID 37299024, 2023). "Transcripts exhibiting significant under expression in trisomic BG01V APCs and CCF-STTG1 astrocytoma cells relative to diploid H9 APCs include several markers of normal differentiated astrocytes, including TRPA1, GABRA2, BDNF, BDKRB1 and BDKRB2." (PMID 20423517, 2010). "In addition, the BDNF response (synthesis and release) of both neurons and astrocytes was studied in vitro by using HT22 hippocampal neuronal cells and C62B astrocytoma cells." (PMID 22581450, 2012). "In rat C62B astrocytomas, both antidepressants increased intracellular BDNF levels at their highest nontoxic concentration." (PMID 22581450, 2012). "C62B astrocytomas did not release BDNF, even after antidepressant treatment." (PMID 22581450, 2012). "No extracellular BDNF was detected in the astrocytoma cell cultures." (PMID 22581450, 2012).
chronic obstructive pulmonary disease (12 papers, 2006 to 2025). A chronic and progressive lung disorder characterized by the loss of elasticity of the bronchial tree and the air sacs, destruction of the air sacs wall, thickening of the bronchial wall, and mucous accumulation in the bronchial tree. "In contrast, few studies reported a relationship between BDNF and cardiac arrhythmias." (PMID 33477900, 2021). "Lower serum irisin levels are associated with mood disturbances, particularly among a cohort of chronic obstructive pulmonary disease (COPD) patients with lower BDNF levels." (PMID 41373506, 2025). "A few studies have focused on the role of BDNF in chronic obstructive pulmonary disease (COPD)-related airway inflammation." (PMID 39064540, 2024). "Our group has formerly reported serum BDNF levels of 345.6 ng/mL (IQR 294.20–387.90 ng/mL) and 314.46 ± 118.68 ng/mL in cohorts of chronic obstructive pulmonary disease patients and bronchial asthma, respectively." (PMID 30952206, 2019). "Among various myokines, the brain-derived neurotrophic factor (BDNF) has been suggested as a myokine that reprograms skeletal muscle and is a possible biomarker of functional capacity in patients with chronic obstructive pulmonary disease (COPD) and in hemodialysis patients." (PMID 39728037, 2024). "This PDE4 inhibitor is typically used in the treatment of chronic obstructive pulmonary disease (COPD) and in this case acts by the indirect inhibition of PTP1B, with the effects mediated by the crosstalk between the CREB/BDNF/TrkB and SIRT1/PTP1B/IGF1 signaling pathways." (PMID 39000142, 2024). "BDNF, on the other hand, seems not to influence the EAR but rather to abrogate chronic airway obstruction." (PMID 16441896, 2006).
cocaine addiction (12 papers, 2013 to 2025). "For instance, in a prospective study, BDNF plasma concentrations were associated in cocaine addiction with relapse risk in early recovery." (PMID 35370811, 2022). "A first study in cocaine dependent individuals found that BDNF concentrations are increased during early abstinence, and the elevated BDNF is predictive of relapse risk during early recovery from cocaine dependence." (PMID 25734326, 2015). "Indeed, serum BDNF concentrations have been recently postulated as an indication of relapse risk during early recovery from cocaine dependence in a prospective study." (PMID 25734326, 2015). "Chronic cocaine addiction promotes PFC DNA methylation at BDNF promoter regions in humans, and histone acetylation in rat DNA increases BDNF transcription in the PFC." (PMID 40226298, 2025). "Several preclinical and clinical studies reported fluctuations of BDNF levels across various phases of cocaine addiction." (PMID 38177347, 2024). "HDAC5 controls the negative regulation of BDNF expression, which is upregulated in cocaine addiction." (PMID 34638996, 2021). "Further research is necessary to elucidate the role of BDNF and IGF-1 in the transition to cocaine addiction and associated psychiatric comorbidity." (PMID 25734326, 2015). "We need to perform additional studies to establish the mechanisms of action of these trophic factors (especially BDNF) and the selectivity in the influence of each factor by a specific comorbid disorder in cocaine addiction." (PMID 25734326, 2015). "It is plausible that specific promoters may contribute to the distinct functions of BDNF in cocaine addiction." (PMID 37189402, 2023). "The role of BDNF/TrkB signaling in cocaine addiction has been documented." (PMID 27735948, 2016). "How, or if, the role of BDNF in reward learning changes throughout the progression of other drug-dependent states remains to be explored, but some studies suggest the role of VTA BDNF may be altered in cocaine dependence." (PMID 26202104, 2016). "DR and BDNF are key molecules involved in cocaine addiction." (PMID 24359524, 2013). "Therefore, BDNF may foster cocaine dependence-related behaviors, particularly behaviors that are related to craving and the risk of relapse." (PMID 38177347, 2024). "Furthermore, BDNF has been also evaluated in cocaine addiction and comorbid disorders." (PMID 25734326, 2015). "By broadening our perspective to incorporate the KEGG pathways, we also observed that ERBB2 (Hypo), NCK1 (Hypo), and JUN (Hyper) are members of the ErbB signaling pathway, while BDNF (Hyper) and JUN (Hyper) are constituents of the Cocaine addiction pathway." (PMID 40217422, 2025). "Although our findings support the importance of monitoring BDNF and IGF-1 in the context of cocaine addiction with psychiatric comorbidity, we are aware of the limitations of the present exploratory study." (PMID 25734326, 2015). "In summary, BDNF, IGF-1 and IGFBP-3 were not affected by a history of pathological use of cocaine supported by the absence of associations with other molecules sensitive to cocaine addiction." (PMID 25734326, 2015). "Although we found no changes in BDNF concentrations, several clinical studies have reported changes in the serum BDNF concentrations of cocaine dependents during abstinence, suggesting that BDNF is a reliable biomarker for cocaine addiction." (PMID 25734326, 2015).
Encephalopathy (12 papers, 2017 to 2024). Encephalopathy is a term that means brain disease, damage, or malfunction. "Enhancing the neural BDNF/TrkB survival pathway via exercise training might be a therapeutic strategy to prevent diabetic-induced neurodegeneration and encephalopathy." (PMID 35743182, 2022).
hepatocellular carcinoma (12 papers, 2011 to 2024). A malignant tumor that arises from hepatocytes. "Immunohistochemical staining of human hepatocellular carcinomas revealed upregulation of BDNF and TrkB protein levels in both tumor and endothelial cells." (PMID 38375479, 2024). "In human hepatocellular carcinoma, BDNF stimulated tumor growth via promoting angiogenic functions of endothelial cells expressing TrkB." (PMID 24403258, 2013). "Moreover, recent data highlighted the indirect inhibitory effect of Api on ROCK-1 expression in hepatocellular carcinoma models in vivo and in vitro as well as the upregulatory effect on BDNF in kindled mice models." (PMID 36943623, 2023). "Treatment with BDNF promoted cell invasion of diverse cancer cells, whereas suppression of BDNF/TrkB signaling abrogated invasion of hepatocellular carcinoma cells, migration and invasion of head and neck squamous cell carcinoma, as well as transitional cell carcinoma." (PMID 24403258, 2013). "Co-transplantation experiments of BDNF-expressing endothelial cells with transformed mouse liver cells showed that high BDNF-expressing endothelial cells could facilitate tumor angiogenesis and growth of hepatocellular carcinomas whereas knockdown of BDNF by short hairpin RNAs impaired such effects." (PMID 38375479, 2024). "However, the roles of BDNF/TrkB in hepatocellular carcinoma (HCC) have been poorly investigated." (PMID 21999199, 2011). "Immunohistochemical analysis revealed significantly elevated expression levels of BDNF and TRKB in hepatocellular carcinoma (HCC)." (PMID 33392191, 2020). "The researchers screened CAR-T cells for brain-derived neurotrophic factor (BDNF) and neurotrophin 4 (NTF4) ligands, and then used a mouse model to create a tumor model by subcutaneously injecting SMMC7721 cells from a human hepatocellular carcinoma cell line." (PMID 38919533, 2024).
Hyperinsulinemia (12 papers, 2011 to 2025). An increased concentration of insulin in the blood. "Some experimental studies have also suggested that hyperphagia, hyperinsulinemia, and higher levels of serum leptin and body weight following a decrease in BDNF levels, among BDNF-knockout mice." (PMID 34580389, 2021). "A study suggests that BDNF may partially compensate for hyperinsulinemia by improving insulin sensitivity, thereby slowing the progression of T2DM." (PMID 40933306, 2025). "BDNF may have an influence on improving fasting glucose and postprandial blood glucose, as well as on hyperinsulinemia reduction." (PMID 32012942, 2020). "Interestingly, a study carried out in bottlenose dolphins characterized by hyperinsulinemia found, by immunolocalization, the presence of NGF and BDNF in the pancreas, which may be involved in the hyperinsulinemia that is observed in dolphins." (PMID 39857710, 2025). "BDNF depletion in the adult VMH elicited increased weight gain, hyperphagia, hyperglycemia, hyperinsulinemia, and hyperleptinemia without affecting locomotor activity." (PMID 38672441, 2024).
meningitis (12 papers, 2011 to 2023). A disorder characterized by acute inflammation of the meninges of the brain and/or spinal cord. "Higher concentrations of BDNF, as well as increased neuronal proliferation, have also been reported in the cerebrospinal fluid of children and adult patients with meningitis or encephalitis." (PMID 37371040, 2023). "The quantification of BDNF in the hippocampus homogenate of the sham and the meningitis rat models showed a significant decrease in the concentration in the infected rats compared to the sham ones." (PMID 36015052, 2022). "BDNF expression decreased in the hippocampus of the meningitis/saline and meningitis/tamoxifen groups when compared with the control/saline group (P < 0.05)." (PMID 29200666, 2017). "In the hippocampus, there were effects for meningitis (F = 167.43; P < 0.001) for treatments (F = 53.30; P < 0.001), as well as interaction (F = 2.80; P = 0.080) in the BDNF." (PMID 29200666, 2017). "Meningitis group showed decreased expression of BDNF and GDNF in the hippocampus while lithium reestablished the neurotrophin expression." (PMID 29200666, 2017). "Although BDNF expression is increased transiently in the brains during the acute phase of meningitis, this endogenous protective mechanism is insufficient to protect neurons from infection-related death." (PMID 28778220, 2017). "Data from two-way ANOVA indicated significant interactions between MyD88 and meningitis on BDNF expression." (PMID 28615695, 2017). "Our previous study showed that increased expression of BDNF following the acute S. pneumonia meningitis was alleviated after antibiotic treatment." (PMID 28615695, 2017). "In this study, we aimed to investigate if activation of the classical inflammatory signaling pathway, namely the MyD88/NF-κB signaling pathway, regulates BDNF expression in experimental S. pneumoniae meningitis." (PMID 28615695, 2017). "The results of our study showed that PI3K/AKT signaling was significantly upregulated after meningitis infection and that this activity was enhanced following BDNF pretreatment." (PMID 28778220, 2017). "Increased BDNF synthesis during the acute phase of meningitis could stimulate the proliferation of dentate granule cells and promote neurogenesis." (PMID 35563321, 2022). "However, lithium as adjuvant treatment reestablished BDNF expression in the meningitis group." (PMID 29200666, 2017). "That BDNF may be a critical neuroprotective mediator is unsurprising given its neuroprotective properties have been identified in a number of neuropathologies including HI, IVH, meningitis, and traumatic brain injury." (PMID 34630028, 2021).
myocardial ischemia (12 papers, 2012 to 2025). A disorder of cardiac function caused by insufficient blood flow to the muscle tissue of the heart. "Research has indicated that TrkB expression in myocardial cells decreases after cardiac ischemia and that the binding of BDNF to p75NTR also diminishes." (PMID 39648800, 2024). "Examination of the mechanisms by which BDNF promotes heart function has indicated that the BDNF–TrkB signaling pathway likely participates in cardioprotective mechanisms following myocardial ischemia/reperfusion injury." (PMID 39648800, 2024). "Further, NF-κB mediated M3 activation down-regulates miR-376b-5p, which promotes myocardial ischemia, possibly by inhibiting brain-derived neurotrophic factor (BDNF) expression." (PMID 35211331, 2022). "Consistently, our previous studies found that exogenous BDNF attenuated myocardial ischemia by inhibiting apoptosis of rat cardiomyocytes." (PMID 33477900, 2021). "Myocardial ischemia preconditioning increases the expression of BDNF mRNA and protein in cardiomyocytes, suggesting that BDNF exerts a protective action against myocardial IR by reducing apoptosis and enhancing antioxidant activity in the heart." (PMID 29744364, 2018). "MiR-376b-5p promotes myocardial ischemia injury possibly by inhibiting BDNF expression and M3-mAChR provides cardioprotection at least partially mediated by the downregulation of miR-376b-5p through NF-κB." (PMID 22396777, 2012). "Although 1134 potential targets of miR-376b-5p were predicted, only a few of them have been reported to be involved in myocardial ischemia, including insulin-like growth factor 2 mRNA binding protein 2, ryanodine receptor 2 and BDNF." (PMID 22396777, 2012). "Given recent studies demonstrating that BDNF was also expressed in the heart where it protected against myocardial ischemia injury, we proposed that BDNF is one potential target of miR-376b-5p in the heart." (PMID 22396777, 2012). "Beyond its well-established role in the nervous system, m-BDNF is increasingly recognized as a pleiotropic molecule involved in various peripheral physiological processes, such as myocardial ischemia protection, promotion of angiogenesis, and regulation of skeletal muscle metabolism." (PMID 40791659, 2025). "Additionally, Opa1 upregulation reduced myocardial ischemia through activation of the Brain-derived neurotrophic factor (BDNF)/tropomyosin-related kinase B (TrkB) pathway." (PMID 32155590, 2020). "Collectively, these studies suggest that BDNF plays numerous roles to orchestrate the repair mechanisms which are activated following acute myocardial ischemia, with distinct actions on hematopoietic cell recruitment, endothelial cell survival, cardiac myocyte function, and cardiac innervation." (PMID 31105581, 2019). "In heart tissue inhibition of BDNF expression by miR-376b-5p supported myocardial ischemia injury." (PMID 30423942, 2018). "In the present study, for the first time, we found that miR-376b-5p inhibited the expression of BDNF and miR-376b-5p promoted H2O2-induced H9c2 cells injury, indicating that miR-376b-5p promoted myocardial ischemia injury possibly by inhibiting the expression of BDNF." (PMID 22396777, 2012). "Our Western blot analysis and luciferase assay experiments demonstrated that miR-376b-5p could directly bind to BDNF gene and inhibit its expression, providing support for our hypothesis that miR-376b-5p promotes myocardial ischemia injury possibly via the downregulation of BDNF." (PMID 22396777, 2012). "The first study to implicate BDNF as a potential therapeutic ligand described the rapid induction of bdnf mRNA and ngf mRNA, but not nt-3 mRNA, following transient cardiac ischemia in the rat." (PMID 31105581, 2019).
obstructive sleep apnea (12 papers, 2019 to 2025). "A correlation between serum BDNF levels and the severity of cognitive impairment in obstructive sleep apnea (OSA) has also been observed." (PMID 38337587, 2024). "In another study on subjects with obstructive sleep apnea (OSA), higher serum BDNF was associated with increased ESS score." (PMID 36984890, 2023). "In patients with obstructive sleep apnea (OSA), recurrent episodes of intermittent hypoxia may stimulate BDNF expression as a compensatory neuroprotective response." (PMID 40565316, 2025). "Other targeted pathways reported for the effects of A. graveolens in neurological disorders include Nrf2 and NF-κB pathways; BDNF/ERK/mTOR (antidepressant); CNTF/CNTFRa/JAK2/STAT3 (cerebral blood flow decreases); and SIRT1/PGC-1a (obstructive sleep apnea)." (PMID 37570794, 2023).